LEP (leptin)
Diseases named in the same sentence as LEP in open-access papers (continued):
Sharing a sentence is not in itself a finding about the gene and the disease.
ovarian cancer (continued). "To date, research has been ongoing into the direct effects of leptin on the development and progression of ovarian cancer." (PMID 37190027, 2023). "They analyzed survival rates in 1656 ovarian cancer patients treated with various chemotherapy programs and found that high leptin level correlates with decreased survival rates." (PMID 37190027, 2023). "A decrease in IL-2, MCP-2/CCL8 and MCP-3/CCL7 levels was detected in both ovarian cancer cell lines with leptin administration." (PMID 37155466, 2023). "The results demonstrate leptin’s inhibitory role in the apoptosis process in ovarian cancer cells, and therefore leptin can be considered an antiapoptotic factor in tumorigenesis." (PMID 37190027, 2023). "An increase in IL-3 and IL-10 expressions, insulin-like growth factor binding proteins (IGFBP) IGFBP-1, IGFBP-2 and IGFBP-3 levels were detected in both ovarian cancer cell lines with leptin administration." (PMID 37155466, 2023). "From the results, it has been shown that leptin increases the proliferation of both ovarian cancer cell lines in a serum-starved medium." (PMID 37155466, 2023). "A growing amount of evidence has confirmed that leptin treatment significantly induces cell growth and proliferation in several ovarian cancer cell lines, including SKOV3, OV-90, A2780, BG-1, and OVCAR3 cells." (PMID 37509120, 2023). "Leptin is similarly known to have proangiogenic and proliferative effects on ovarian cancer and promotes tumor progression." (PMID 37375634, 2023). "Insulin-like growth factor binding proteins (IGFBP) IGFBP-1, IGFBP-2 and IGFBP-3 were increased by leptin treatment in both ovarian cancer cells." (PMID 37155466, 2023). "The researchers obtained similar results to previous ones, which indicate that leptin stimulates the proliferation of ovarian cancer cells and the growth of ovarian cancer cells correlated with higher leptin concentrations in the medium." (PMID 37190027, 2023). "In a study ofa group of patients with ovarian cancer, mean leptin concentration was significantly higher in patients with lower stages of advancement (stage I and II compared to stage III and IV)." (PMID 37444627, 2023). "On the other hand, a clinical trial showed that the ovarian cancer group exhibited lower levels of leptin compared to the group with benign ovarian masses in pulled premenopausal and postmenopausal women." (PMID 37509120, 2023). "In conclusion; leptin has a proliferative effect on human ovarian cancer cell lines and affects different cytokines in different types of ovarian cancer cells." (PMID 37155466, 2023). "Accordingly, a Kaplan–Meier analysis suggested that leptin overexpression is a positive prognosticator of disease-free survival (DFS) along with disease-specific survival (DSS) in ovarian cancer patients." (PMID 37509120, 2023). "It was shown that leptin has a proliferative effect on human ovarian cancer cell lines and affects different cytokines in different types of ovarian cancer cells." (PMID 37155466, 2023). "Our exercise intervention among women with ovarian cancer resulted in changes in two prespecified biomarkers in the exercise group compared to the attention‐control group, a 57.4% reduction in serum leptin and a 14.9% reduction in IGF‐1." (PMID 37269192, 2023). "A reduction in this antiangiogenic molecule was detected in MDAH 2774 ovarian cancer cell line with leptin application." (PMID 37155466, 2023). "Leptin helps maintain the cancer stem cell-like properties of ovarian cancer cells and stimulates the migration and invasion of ovarian cancer cells." (PMID 36755926, 2023). "In this study, for the first time in the literature, the effects of leptin on the levels of cytokines in ovarian cancer cells have been revealed." (PMID 37155466, 2023). "They treated ovarian cancer cells of both lines with different leptin concentrations, ranging from 20–200 ng/mL." (PMID 37190027, 2023).
ovarian cancer (continued). "Within these pathways are factors HIF-1α, IGFBPs, GLUT1, FASN, and leptin, which have all been demonstrated to be potential therapeutic targets in ovarian cancer." (PMID 36230617, 2022). "In a recent study in ovarian cancer, longer disease-specific survival (57 months) has been seen in women with low leptin to adiponectin ratios compared to those with medium or high levels (49 and 37 months, respectively)." (PMID 34751020, 2022). "In ovarian cancer, leptin was shown to induce MMP7 (known to degrade collagen type IV, laminin, and fibronectin) and promote invasiveness by activating ERK and JNK pathways." (PMID 35565396, 2022). "Leptin proliferative effects on ovarian cancer cell lines OVCAR-3 and A2780, after transfection with estrogen receptor-α, has also been described." (PMID 34751020, 2022). "Through the activation of JAK/STAT and PI3K pathways, leptin stimulates ovarian cancer cell growth and prevents cell apoptosis." (PMID 36230617, 2022). "While serum leptin levels are reduced in patients with ovarian cancer, the expression of leptin and its receptors are upregulated in ovarian cancer tissue." (PMID 34751020, 2022). "Leptin also enhances ovarian cancer progression through conservation of stem cells and mesenchymal characteristics of the cancer cells." (PMID 34751020, 2022). "Leptin has been shown to contribute to metastatic advancement of epithelial ovarian cancer by assisting cell migration and tissue invasion by binding to OB-Rb mediated via JAK/STAT3, MAPK, AKT, mTOR, RhoA/ ROCK, and MYPT1 signaling pathways." (PMID 34751020, 2022). "Poorer outcomes in epithelial ovarian cancer were correlated with enhanced levels of leptin, as well as the expression of its receptor and the leptin to adiponectin ratio." (PMID 34751020, 2022). "ERα instead of ERβ can participate in the invasion of ovarian cancer cells induced by leptin in an estrogen-independent manner, and 17β-estradiol can reverse the migration of ovarian cancer cells induced by leptin through the PI3K/Akt signaling pathway." (PMID 34485124, 2021). "The biological effect of leptin on inducing ovarian cancer cell growth was mediated by an increase in cyclin D1 and Mcl-1 expression after the activation of the PI3K/Akt and MEK/ERK1/2 signaling axes." (PMID 33799880, 2021). "Cancer-associated adipocytes, CAAs, exhibit an inflammatory phenotype, releasing cytokine/chemokine adipokines, i.e., leptin, adiponectin, interleukin-6 (IL-6), and IL-8 that contribute to ovarian cancer cell metastatic colonization." (PMID 34677277, 2021). "This study revealed that PI3K/Akt/mTOR pathway induced by leptin is involved in OC peritoneal metastasis formation and interestingly showed a novel potential therapeutic target for ovarian cancer." (PMID 33809784, 2021). "A cohort study enrolling ovarian cancer patients indicated a significant correlation of leptin and leptin receptor coexpression with shorter survival time." (PMID 33799880, 2021). "Leptin levels also exhibited a positive correlation with poor prognosis in ovarian cancer, and high leptin levels were found in multiple myeloma patients and to correlate with clinical stage." (PMID 33799880, 2021). "Median expression of leptin at 6025.32 pg/ml was almost three times lower in samples with ovarian cancer compared to the control group with a median expression of 17,867.52 pg/ml." (PMID 34530759, 2021). "Trial on five plasma biomarkers (CA125, HE4, OPN, leptin, prolactin) and their possible role in differentiating benign from malignant ovarian tumors." (PMID 34530759, 2021). "With a logistical regression model a formula including CA125, HE4, OPN, leptin and prolactin was developed to predict malignant ovarian tumors." (PMID 34530759, 2021). "Several mechanisms have been investigated to explicate the role of leptin in ovarian cancer progression." (PMID 34440886, 2021).
ovarian cancer (continued). "Various types of cancer show elevated leptin plasma levels, whereas reduced plasma leptin levels have been observed in ovarian cancer patients." (PMID 34530759, 2021). "Treatment with exogenous leptin decreased paclitaxel/docetaxel-induced G2/M phase cell cycle arrest in ovarian cancer cells." (PMID 33799880, 2021). "In summary, there is a vast majority of studies that confirm a remarkable correlation between lower expression of adiponectin, higher expression of leptin and ovarian cancer." (PMID 33809784, 2021). "In ovarian cancer, leptin was found to induce matrix metalloproteinase 7 expression to promote cell invasion by activating ERK and JNK pathways." (PMID 33804101, 2021). "Leptin-induced ovarian cancer cell invasion via overexpression of MMP7, MMP9, and uPA was reported, and the involvement of the estrogen-independent role of ERα in regulating the phenotype was indicated." (PMID 33799880, 2021). "Substantially larger levels of leptin than the physiological level were observed in: bladder cancer; breast cancer; large B cell lymphoma; ovarian cancer; and testicular cancer, inter alia." (PMID 32531934, 2020). "In the BG-1, OVCAR-3, and SKOV-3 ovarian cancer cells, the expression of the short and long isoforms of ObR was seen; furthermore, in BG-1 cells, leptin-dependent MAPK/ERK1/2 activation and proliferation were observed." (PMID 33334030, 2020). "Some authors analyzed serum levels of APN and leptin in 52 patients with ovarian cancer, showing that both APN and leptin concentrations were significantly lower in women with ovarian cancer than in healthy individuals." (PMID 31212761, 2019). "Studies suggest that the binding of leptin to its receptor (OB-Rb), activates the signaling pathways for ovarian cancer progression, particularly in obese women, resulting in a poor survival rate." (PMID 31245287, 2019). "In the case of ovarian cancer cell proliferation, Leptin, a hormone secreted by adipose tissue interlinks obesity and EOC progression." (PMID 31861720, 2019). "Leptin induces matrix metalloproteinase 7 expression to promote ovarian cancer cell invasion by activating ERK and JNK pathways (Ghasemi, Hashemy, Aghaei, & Panjehpour, 2018)." (PMID 30478982, 2019). "Generally ovarian cancers arise in the surface epithelial cells, and the majority of studies pertaining to leptin have focused on this group of malignancies." (PMID 30510663, 2018). "Actually, recombinant leptin was reported to notably promote ovarian cancer migration, invasion, peritoneal metastasis and epithelial-mesenchymal transition (EMT) via signaling pathway PI3K/Akt/mTOR." (PMID 29682217, 2018). "A study in ovarian cancer cohort significantly showed the correlation of leptin and leptin receptor co-expression with shorter patient survival." (PMID 29682217, 2018). "Different ovarian cancer cell lines usually have shown cellular growth and proliferation in response to leptin treatment." (PMID 30510663, 2018). "Using different ovarian cancer cell lines (OVCAR-3, SKOV3 and CaoV-3), a recent report found that leptin induced ovarian cancer cell invasion via up-regulation of uPA." (PMID 30510663, 2018). "Leptin is an adipocyte-derived adipokine that plays a crucial role in regulating appetite and energy balance, that is strongly elevated in obese ovarian cancer patients." (PMID 30157901, 2018). "This indicates that leptin can utilize multiple pathways to influence cancer cell migration, although we showed that in ovarian cancer cells inhibition of the JAK2/STAT3 pathway was sufficient to block this effect." (PMID 29212170, 2017). "Taken together, these results indicate that stimulation of ovarian cancer cell growth by leptin involves, at least in part, ERα transcriptional activation via STAT3 signaling pathways." (PMID 28750624, 2017).
ovarian cancer (continued). "Analysis of ovarian cancer cell lines expressing functional LEPR revealed that leptin induced proliferation of adenocarcinoma cell lines and stimulated both survival and migration in both adenocarcinoma and teratocarcinoma cell types." (PMID 29212170, 2017). "Two previous studies have demonstrated leptin-mediated proliferation of ovarian cancer cells via the MAPK pathway and PI3K pathways." (PMID 29212170, 2017). "This study identified leptin-induced migration of LEPR-positive ovarian cancer cells mediated via JAK2/STAT3." (PMID 29212170, 2017). "Both leptin and OB3 stimulated the phosphorylation of STAT3, but only leptin promoted the proliferation of ovarian cancer cells." (PMID 28750624, 2017). "It was shown that leptin stimulates the proliferation of ovarian epithelial cancer cells partially mediated via aromatase and ERα." (PMID 28750624, 2017). "Leptin also facilitates the maintenance of stemness and the mesenchymal phenotype of ovarian cancer cells." (PMID 26751490, 2016). "Leptin has been shown to stimulate ovarian cancer cell migration and invasion potential through the activation of JAK/Stat3, PI3K/Akt, and RhoA/ROCK signaling in cancer cells and subsequent stress fiber and focal adhesion formation." (PMID 26751490, 2016). "Ovarian cancers expressing high levels of leptin or OB-Rb mRNAs have a worse overall survival, particularly in stage IIIC patients (81 of 419 cases)." (PMID 26053184, 2015). "Recent studies have suggested that higher circulating levels of leptin, higher leptin receptor expression by the tumor and a high leptin to adiponectin (L:A) ratio all correlate with a worse outcome in several epithelial cancers, including ovarian cancer." (PMID 26053184, 2015). "Using high leptin concentrations, the magnitude of the effect is quite similar in all ovarian cancer cell lines tested, despite the differences in receptor expression." (PMID 26053184, 2015). "As mentioned in the introduction, two studies have shown that high circulating leptin levels or high OB-Rb expression in the primary tumor correlate with poorer outcomes in ovarian cancer." (PMID 26053184, 2015). "To directly explore the biological effects of leptin and OB-Rb levels in ovarian cancer cells, we chose to use cell lines and primary tissue cultures representing the two types of serous ovarian cancer." (PMID 26053184, 2015). "By blocking binding with a leptin-neutralizing antibody, we confirmed that leptin binding to OB-Rb is required for the increase in cell migration and invasion observed in the ovarian cancer cell lines." (PMID 26053184, 2015). "Here, we confirmed that leptin indeed increased cell proliferation in ovarian cancer cells, but only in the OB-Rb high-expressing cancer cells (A2780, UCI 101)." (PMID 26053184, 2015). "Leptin also contributed to the maintenance of stemness and the mesenchymal phenotype in ovarian cancer cells." (PMID 26053184, 2015). "Our findings demonstrate that leptin stimulated ovarian cancer cell migration and invasion, offering a potential explanation for the poor prognosis among obese women." (PMID 26053184, 2015). "High OB-Rb expression and high circulating levels of leptin have been correlated with poorer outcomes in epithelial ovarian cancer." (PMID 26053184, 2015). "In vitro and preclinical in vivo data suggest that leptin acts as a mitogenic agent to promote prostate, breast, and ovarian cancer cell growth and/or enhances cancer angiogenesis and migration." (PMID 24587106, 2014). "For miR183-96-182 cluster, Xu reported that overexpressed miR-182 and miR-96 targeting fork head box O3 plays a significant role in the pro-proliferation effect of leptin on ovarian cancer cells." (PMID 24816756, 2014). "Leptin has been reported to induce proliferation of ovarian cancer cells in vitro and overexpression of leptin receptor has been linked to unfavorable prognosis in ovarian cancer patients." (PMID 25026276, 2014).
ovarian cancer (continued). "Recently, a link has been found between the postmenopausal hormonal therapy and the effect of BMI on ovarian cancer prognosis; and given the role of the leptin in progression of various cancers, a hormonal mechanism is suggested." (PMID 27382614, 2014). "In vitro studies have demonstrated that leptin induces proliferation in the ovarian cancer cell line BG-1, and it has been shown to inhibit apoptosis in ovarian epithelial cancer cell lines SKOV3 and MDAH2774." (PMID 22968658, 2013). "Leptin is an adipokine produced predominantly by adipocytes and leptin-mediated signaling has been shown to promote ovarian cancer cell growth in vitro." (PMID 24093089, 2013). "Taking into consideration the limitations of in vitro studies, in vivo studies should be performed to confirm leptin’s contribution to ovarian cancer progression." (PMID 22968658, 2013). "Accumulating evidence indicates that leptin has an effect on ovarian cancer growth, but information on its molecular mechanism with respect to regulation of the cell cycle and apoptosis is limited." (PMID 22968658, 2013). "Several studies have addressed the possible role of leptin, the product of the obesity gene (Ob), in ovarian cancer development and progression." (PMID 22968658, 2013). "Leptin promotes ovarian cancer cell line growth by up-regulating genes and proteins responsible for inducing cell proliferation as well as down-regulating pro-apoptotic genes and proteins in apoptotic pathways." (PMID 22968658, 2013). "We evaluated the effects of leptin on cell proliferation and apoptosis in the human ovarian cancer cell line OVCAR-3." (PMID 22968658, 2013). "Surprisingly, data concerning the anti-apoptotic actions of leptin in ovarian cancer cells are limited." (PMID 22968658, 2013). "In conclusion, our results are the first to demonstrate the molecular mechanism involved in the regulation of the cell cycle and apoptosis by leptin in an epithelial ovarian cancer cell line." (PMID 22968658, 2013). "In pancreatic and ovarian cancers, leptin–ObR signalling promotes extracellular matrix remodelling, migration, and invasion through upregulation of matrix metalloproteinase-13, an enzyme that breaks down the extracellular matrix, particularly collagen, and downstream effectors." (PMID 41586225, 2025). "For ovarian cancer, metabolic changes such as high insulin and leptin levels may trigger cancer through pathways like PI3K/AKT/mTOR and weaken immune responses." (PMID 41189943, 2025). "In ovarian cancer cells, leptin maintains stem-like characteristics and drives a more aggressive transcriptional phenotype, explaining the poor prognosis observed in obese patients with leptin resistance or chronic hyperleptinaemia." (PMID 41586225, 2025). "The role of leptin is still controversial in ovarian cancer." (PMID 37509120, 2023). "Indeed, one study demonstrated that overweight ovarian cancer patients who exhibit higher levels of leptin as well as ObR expression in serum and ascites isolated from metastatic patients demonstrate worse overall survival (OS)." (PMID 37509120, 2023). "Leptin increases the proliferation of both ovarian cancer cell lines." (PMID 37155466, 2023). "According to the authors, the ratio of CA125 and leptin may be useful biomarkers for diagnosing ovarian cancer, but this requires further analysis." (PMID 37190027, 2023). "The aim of the study was to investigate the effects of leptin on human ovarian cancer cells." (PMID 37155466, 2023). "Here, we aimed to clarify the molecular mechanisms of leptin in ovarian cancer cells." (PMID 37155466, 2023). "The expression of uPA induced by leptin mediates ovarian cancer cell invasion." (PMID 37605299, 2023). "Moreover, to elucidate the molecular mechanisms of leptin in ovarian cancer cells, changes in the expression levels of 80 cytokines were evaluated after leptin treatment via a human cytokine antibody array." (PMID 37155466, 2023).